RNF24 (ring finger protein 24)
Description:
May play a role in TRPCs intracellular trafficking.
Synonyms: G1L
Tractability: Antibody: UniProt predicts a signal peptide or a membrane-spanning region. PROTAC: ubiquitination databases record sites on it.
Gene: Protein-coding gene on chromosome 20 (3,927,309 to 4,015,591, reverse strand). Ensembl gene ENSG00000101236.
Subcellular location: Golgi apparatus membrane
Subcellular location (Human Protein Atlas): Golgi apparatus
Gene Ontology:
Molecular function: protein binding; zinc ion binding
Cellular component: Golgi apparatus; Golgi membrane
Genetic constraint (gnomAD): Loss-of-function variants: 9 observed, 12.85 expected, observed/expected ratio (o/e) 0.7, 90% interval 0.42 to 1.22. The upper end of that interval is the gene's LOEUF score, 1.22, which puts it in group 5 of 6, group 1 being the genes least tolerant of losing a copy. Missense variants: 85 observed, 123.48 expected, observed/expected ratio (o/e) 0.69, 90% interval 0.58 to 0.82. Synonymous variants: 35 observed, 45.79 expected, observed/expected ratio (o/e) 0.76, 90% interval 0.58 to 1.01.
Homologues: Orthologues: chimpanzee RNF24 (100% identical), dog RNF24 (100% identical), macaque RNF24 (100% identical), guinea pig RNF24 (99% identical), pig RNF24 (99% identical), rabbit RNF24 (99% identical), mouse Rnf24 (98% identical), rat Rnf24 (98% identical), tropical clawed frog rnf24 (92% identical), zebrafish rnf24 (85% identical), Caenorhabditis elegans T22B2.1 (23% identical), Caenorhabditis elegans C09E7.7 (22% identical), and 5 more. Paralogues in human: RNF122 (54% identical).
Diseases named in the same sentence as RNF24 in open-access papers:
RNF24 is named in the same sentence as 13 diseases in open-access papers, as found by Europe PMC text mining. Sharing a sentence is not in itself a finding about the gene and the disease. The quoted sentences say what the papers report.
esophageal adenocarcinoma (3 papers, 2018 to 2023). A malignant tumor with glandular differentiation arising predominantly from Barrett mucosa in the lower third of the esophagus. "Some researchers have reported that RNF24 plays a role in the progression of Barrett's esophagus to esophageal adenocarcinoma." (PMID 33490245, 2020). "Moreover, RNF24 expression is more than 2-fold upregulated in esophageal adenocarcinoma patients compared to normal subjects." (PMID 37051238, 2023).
breast carcinoma (1 paper, 2024). "In breast cancer, RNF24 acts in conjunction with HER2 protein to accelerate the ubiquitination and degradation of HER2, thereby inhibiting the proliferation and invasion of tumour cells." (PMID 38534087, 2024).
depression (1 paper, 2024). "As a result, we discovered 43 key genes associated with pain–depression comorbidity, along with the identification of RNF24, MGAM, FOS, TKT, and SIGLEC5 as hub genes." (PMID 39125922, 2024). "The five hub genes, RNF24, MGAM, FOS, and TKT, were deemed potential diagnostic and prognostic markers for patients with pain–depression comorbidity." (PMID 39125922, 2024).
lung carcinoma (1 paper, 2024). "In lung cancer, the expression level of RNF24 is significantly upregulated, and it is involved in the regulation of the NF‐κB signalling pathway, promoting the proliferation and invasion of tumour cells." (PMID 38534087, 2024).
neuropathy (1 paper, 2025). A disorder affecting the nervous system that manifests with pain, tingling, numbness, and/or muscle weakness. "For neuropathy, rs34904346 (p = 2.0 × 10−5) was an expression quantitative trait locus (eQTL) for RNF24 in nerve tissue, with three other RNF24 eQTLs associated with neuropathy (p < 0.01)." (PMID 40913328, 2025).
osteoporosis (1 paper, 2024). A condition of reduced bone mass, with decreased cortical thickness and a decrease in the number and size of the trabeculae of cancellous bone (but normal chemical composition), resulting in increased fracture incidence. "In the mouse experiment, FAM129A and anti‐RNF24 were found to partially alleviate the progression of osteoporosis." (PMID 38534087, 2024).
tumor (3 papers, 2020 to 2024). "Recent studies have demonstrated the crucial role of RNF24 in various tumours." (PMID 38534087, 2024). "Interestingly, as depicted in the Polar chart, when considering the specific gene deregulation associated to drug sensitivity, CTNNBL1, RNF24 and TTI1 showed in primary HGSOC cell lines the same trend observed in tumor tissue from HGSOC patients." (PMID 35120576, 2022). "Interestingly, we showed that CTNNBL1, RNF24 and TTI1 are associated to resistance to therapy in both primary HGSOC cell lines and patients’ samples, in line with available literature data on the role of these proteins as tumor cell-derived resistance factors." (PMID 35120576, 2022). "RNF24 may affect the proliferation of tumor cells by affecting cell metabolism." (PMID 33490245, 2020). "Cytotoxicity assays, combined with gene-expression analysis in primary HGSOC cell lines, allowed to define CTNNBL1, RNF24, and TTI1 as cell-autonomous contributors to tumor resistance." (PMID 35120576, 2022).
cancer (2 papers, 2022 to 2025). A tumor composed of atypical neoplastic, often pleomorphic cells that invade other tissues. "The direction of association between RNF24 expression and cisplatin sensitivity (AUC) in cancer cells (n = 575) was as expected (R = −0.052), but not significant (p = 0.21)." (PMID 40913328, 2025). "Lastly, RNF24 is a membrane protein which interacts with TRPC (transient receptor potential channel) proteins and, although literature data have suggested that it may act as a cancer-promoting factor in different tumors, its mechanistic role is still to be uncovered." (PMID 35120576, 2022).
RNF24 also shares sentences with these, for which no sentence is quoted: Barrett esophagus (1 paper); infection (1); neurotoxicity (1); oral squamous cell carcinoma (1); Vertigo (1).